ZNF574 (zinc finger protein 574)
Description:
Part of a ribosome quality control that mediates surveillance of ribosome assembly and promotes degradation of ribosomes with assembly defects.
Synonyms: FLJ22059; FP972
Tractability: PROTAC: ubiquitination databases record sites on it; its protein half-life has been measured.
Gene: Protein-coding gene on chromosome 19 (42,068,477 to 42,081,552, forward strand). Ensembl gene ENSG00000105732.
Subcellular location: Cytoplasm; Nucleus
Subcellular location (Human Protein Atlas): Nucleoplasm; Vesicles
Gene Ontology:
Molecular function: protein binding; ribosomal large subunit binding; transcription cis-regulatory region binding
Biological process: cytosolic ribosome assembly; regulation of ribosome biogenesis; ribosome-associated ubiquitin-dependent protein catabolic process; regulation of transcription by RNA polymerase II
Cellular component: cytoplasm; nucleus
Genetic constraint (gnomAD): Loss-of-function variants: 25 observed, 58.25 expected, observed/expected ratio (o/e) 0.43, 90% interval 0.31 to 0.6. The upper end of that interval is the gene's LOEUF score, 0.6, which puts it in group 2 of 6, group 1 being the genes least tolerant of losing a copy. Missense variants: 1,065 observed, 1,276.5 expected, observed/expected ratio (o/e) 0.83, 90% interval 0.79 to 0.88. Synonymous variants: 543 observed, 518.49 expected, observed/expected ratio (o/e) 1.05, 90% interval 0.98 to 1.12.
Homologues: Orthologues: chimpanzee ZNF574 (99% identical), macaque ZNF574 (99% identical), guinea pig ZNF574 (95% identical), rabbit ZNF574 (95% identical), dog ZNF574 (95% identical), rat Zfp574 (94% identical), mouse Zfp574 (94% identical), pig ZNF574 (94% identical), tropical clawed frog znf574 (47% identical), Drosophila melanogaster mld (10% identical), zebrafish zgc:66472 (8% identical). Paralogues in human: ZNF526 (27% identical), ZNF91 (22% identical), ZNF208 (22% identical), ZNF84 (22% identical), ZNF107 (21% identical), ZNF160 (21% identical), ZNF99 (21% identical), ZNF729 (21% identical), ZNF420 (21% identical), ZNF594 (21% identical), ZNF473 (20% identical), ZNF845 (20% identical), and 24 more.
Diseases named in the same sentence as ZNF574 in open-access papers:
ZNF574 is named in the same sentence as 8 diseases in open-access papers, as found by Europe PMC text mining. Sharing a sentence is not in itself a finding about the gene and the disease. The quoted sentences say what the papers report.
neuroblastoma (1 paper, 2018). Neuroblastoma (NB) is the most common solid, extracranial childhood tumor. "The third gene mutated in both murine and human neuroblastoma is ZNF574 (murine ortholog Zfp574)." (PMID 29492199, 2018). "Comparative cross species analysis of all 25 non-synonymous coding mutated genes detected in the mouse models resulted in three matches (DICER1, ZNF574 and PTCH1) in the list of 883 genes reported to harbor non-synonymous coding mutations in human neuroblastoma." (PMID 29492199, 2018).
Obesity (1 paper, 2022). Accumulation of substantial excess body fat. "Down-regulation of IL17RA, a downstream gene of ZNF574 (the hub gene in the pink module), was found to reduce the side effects of obesity in mice fed with high energy diet for 9 weeks." (PMID 36439361, 2022).
ZNF574 also shares sentences with these, for which no sentence is quoted: asthma (1 paper); breast carcinoma (1); metabolic syndrome (1); ovarian carcinoma (1); Temple syndrome (1); Williams syndrome (1).